APP (amyloid beta precursor protein)
Diseases named in the same sentence as APP in open-access papers (continued):
Sharing a sentence is not in itself a finding about the gene and the disease.
Alzheimer disease (continued). "Studies have shown that the CpG site on the APP gene promoter is hypomethylated in Alzheimer's disease (AD) of the brain, causing the overexpression of amyloid precursor protein, hence overproduction and abnormal metabolism of Aβ." (PMID 36941702, 2023). "The pathogenic mechanisms of Alzheimer’s disease (AD) are still poorly characterized, but a hallmark is the aberrant processing of the amyloid precursor protein (APP) mediated by γ-secretase." (PMID 37759703, 2023). "Alzheimer's disease (AD) is a progressive memory loss and cognitive dysfunction brain disorder brought on by the dysfunctional amyloid precursor protein (APP) processing and clearance of APP peptides." (PMID 38130706, 2023). "Amyloid precursor protein (APP) is a key molecule in the pathogenesis of Alzheimer's disease (AD) as the pathogenic amyloid-β peptide is derived from it." (PMID 37387352, 2023). "The group inserted several APP short fragments into live neurons to understand better the phenomenon of neuronal loss in Alzheimer’s disease and they discovered that one fragment, called Jcasp, interacting with SET, induced neuronal cell death." (PMID 36345878, 2022). "It is worth noting that beta-amyloid (Aβ) produced by APP, a pathological sign of Alzheimer's disease, causes inflammatory damage to neurons and is responsible for the degeneration of synapses and the apoptosis of neurons." (PMID 35525962, 2022). "Here, we demonstrate that tubulin acetylation accumulates in post-mortem brain tissues from Alzheimer’s disease patients and human neurons harboring the Alzheimer’s familial APP-V717I mutation." (PMID 36092705, 2022). "Adults with Down syndrome (DS) have a triplicated copy of chromosome 21 with overexpression of the amyloid precursor protein (APP) gene as the main contributor to the high risk of Alzheimer’s disease (AD) in this population." (PMID 35669316, 2022). "APP is mainly associated with Alzheimer's disease and participates in the control of epidermal wound repair." (PMID 35435317, 2022). "APP (amyloid-beta precursor protein) mutations severely affect sleep status in Alzheimer’s disease model mice." (PMID 35958162, 2022). "Their results showed increased amounts of β-amyloid protein and amyloid precursor protein (APP), which are both known to be associated with Alzheimer's disease (AD)." (PMID 35242784, 2022). "Mutations of the APP gene are associated with Alzheimer’s disease (AD), in which the amyloid β-peptide is the principal constituent of the senile plaques, the major AD hallmark." (PMID 35650588, 2022). "Familial Alzheimer's disease (FAD) is caused by dominantly inherited mutations in APP, PSEN1 and PSEN2." (PMID 34319632, 2022). "We induced bilateral hippocampal overexpression of Gas6 in the APP/PS1 model of Alzheimer’s disease with stereotactic injections of an adeno-associated virus containing Gas6." (PMID 35130912, 2022). "APP is a cell surface receptor and transmembrane precursor protein, initially associated with Alzheimer disease; however, recent reports indicate that it harbors antimicrobial activity." (PMID 36313672, 2022). "The first discovered gene causing AD was APP, located on the 21q21 chromosome, and mutations of this gene are linked to early-onset Alzheimer’s disease (EOAD)." (PMID 35563001, 2022). "Presenilin 2 (Psen2), which cleaves proteins such as APP (amyloid-beta precursor protein) and has been shown to cause Alzheimer’s disease, displays a change in ASE (Fisher’s exact; q = 0.00001) and a 2.7-fold decrease in RNA transcript levels." (PMID 35485945, 2022). "Translational work on aspartyl IPs has focused on γ-secretase owing to its processing of the amyloid precursor protein (APP) associated with Alzheimer’s disease." (PMID 35471152, 2022). "Blueberry extract (150 mg/kg/day) containing anthocyanins promoted neuronal autophagy to decrease neuronal damage in transgenic APP/PS1 mice with mutations associated with early-onset Alzheimer’s disease." (PMID 35631301, 2022).
Alzheimer disease (continued). "Mutations in genes encoding presenilin 1 or 2 (PSEN1 or PSEN2) and amyloid precursor protein (APP) have been linked to early-onset Alzheimer’s disease." (PMID 36077172, 2022). "The APP/γ-secretase pathway seems to be involved in the control of the hypoxia response, and other proteins linked to Alzheimer’s disease pathology, for example, the Notch protein." (PMID 36077172, 2022). "The APP is cleaved by the γ-secretase and β-secretase enzymes that produce Aβ, which accumulates in the form of plagues and can cause Alzheimer’s disease." (PMID 36286029, 2022). "Amyloid-β (Aβ) derived from amyloid precursor protein (APP) hydrolysis is acknowledged as the predominant hallmark of Alzheimer’s disease (AD) that especially correlates to genetics and daily activities." (PMID 36016856, 2022). "Triplication of the APP gene on human chromosome 21 is linked to Alzheimer’s disease (AD)-like neuropathology in DS patients." (PMID 34982276, 2022). "Heritable mutations affecting the APP gene were the first to be discovered to cause Alzheimer’s disease (AD)." (PMID 35247387, 2022). "We then examined amyloid-β (Aβ) plaque load as a hallmark of Alzheimer’s disease in the hippocampus and cortex of APP/PS1 and APP/PS1-IL37tg animals." (PMID 36040311, 2022). "As to the role of aluminum in the pathogenesis of Alzheimer’s disease, it seems to basically consist in promoting the oligomerization of peptides produced from APP by β- and γ-secretases, which raises the risk of Aβ aggregate formation." (PMID 36045741, 2022). "The beneficial effects of a partial loss of function of JNK1 in a genetic model of Alzheimer’s disease (APP/PS1/Jnk1±) was reported in the past by our research group." (PMID 35508978, 2022). "The amyloid-β precursor protein (APP) undergoes proteolysis by β- and γ-secretases to form amyloid-β peptides (Aβ), which is a hallmark of Alzheimer’s disease (AD)." (PMID 35464218, 2022). "The β-secretase BACE1 cleaves APP at the N-terminus of the Aβ domain, which is the first step in the formation of pathogenic Aβ in Alzheimer’s disease." (PMID 35900966, 2022). "Of relevance, recently, in the latest Alzheimer’s disease GWAS, the amyloid precursor protein gene (APP) has finally been found to be associated with a risk of late-onset Alzheimer’s disease." (PMID 36077172, 2022). "Increased levels of inflammatory cytokines and NF-kB promote a rise in amyloid precursor protein (APP) and Aβ protein cleavage and accumulation, resulting in neuron loss and the development of Alzheimer’s disease." (PMID 35684340, 2022). "PreP also degrades amyloid β (Aβ), the cleavage product of the amyloid precursor protein (APP) that is linked to the progression of Alzheimer’s disease and is imported into mitochondria, particularly synaptic mitochondria." (PMID 35383169, 2022). "These animals had mutations in the APP and presenilin transgenes that are typical for hereditary (familial) forms of Alzheimer’s disease." (PMID 36555569, 2022). "The pre-symptomatic stage of Alzheimer’s disease (AD) is associated with increased amyloid-β (Aβ) precursor protein (APP) processing and Aβ accumulation in the retina and hippocampus." (PMID 35626688, 2022). "The higher production of amyloid precursor protein (APP), the precursor peptide of beta-amyloid, predisposes persons with DS to early Alzheimer's disease (AD)." (PMID 36110433, 2022). "Alzheimer’s disease (AD) involves pathological processing of amyloid precursor protein (APP) into amyloid-β and microtubule associated protein Tau (MAPT) into hyperphosphorylated Tau tangles leading to neurodegeneration." (PMID 36151233, 2022). "An exciting application of the use of mouse panels in translational research comes from crossing the classical Alzheimer’s disease (AD) mouse model (5XFAD) bearing mutations in APP and PSEN1 with 28 different strains of the BXD panel (AD-BXD)." (PMID 35886916, 2022).
Alzheimer disease (continued). "In pathological conditions, the proteolysis of APP generates Aβ peptides, which accumulate to form Aβ plaques, a hallmark of Alzheimer’s disease (AD)." (PMID 35676735, 2022). "Alzheimer's disease (AD) is a neurodegenerative pathology linked to both, abnormal amyloid precursor protein (APP) processing, generating Aβ peptide, and Tau hyperphosphorylation and aggregation." (PMID 36408110, 2022). "Accumulation of C99 and Aβ is a hallmark of the pathogenic amyloidogenic cascade in Alzheimer’s disease (AD), while C83 is the major physiological APP fragment generated by human and murine neurons." (PMID 35277173, 2022). "Defects in SORLA have been implicated in the pathogenesis of Alzheimer’s disease due to the protein’s role as an intracellular sorting receptor, including for amyloid precursor protein (APP), the precursor to Aβ." (PMID 33902009, 2021). "Genes within Alzheimer’s disease risk loci are enriched in multiple diverse biological pathways: such as the immune response, cholesterol metabolism, amyloid protein processing and APP metabolism." (PMID 33959712, 2021). "APP, a well-known gene involved in neurodegenerative diseases such as Alzheimer’s disease, has been implicated as a regulator of synapse formation and neural plasticity." (PMID 34413720, 2021). "Many studies have demonstrated that transgenic mice with expression of human APP carrying Alzheimer disease–causing mutations in the brain have high levels of toxic Aβ, neuronal pathophysiology, memory impairments, and plaque formation." (PMID 34525093, 2021). "In Alzheimer's disease, it is thought that retromer loss of function results in failure to recycle SorLA, resulting in retention of APP in endosomes, where APP can be processed by β- and γ-secretase to generate aberrantly large quantities of Aβ." (PMID 33380435, 2021). "Processing of the amyloid precursor protein (APP) via the amyloidogenic pathway is associated with the etiology of Alzheimer’s disease." (PMID 33839158, 2021). "For Alzheimer’s disease, striking genetic analyses have shown that human mutations in APP that promote the production of A-ß also promote Alzheimer’s disease and mutations that specifically reduce A-ß production confer resistance." (PMID 34718534, 2021). "Altered amyloid precursor protein (APP) processing potentiates the aggregation of glycation products, and amyloid-β (Aβ) toxicity is a key pathogenic feature of Alzheimer’s disease (AD)." (PMID 34206588, 2021). "The strong association of C99 with disordered domains occurred independently of its cholesterol-binding activity or homodimerization, or of the presence of the familial Alzheimer disease Arctic mutation (APP E693G)." (PMID 33839158, 2021). "DS is also associated with an increased prevalence and early onset of Alzheimer’s disease (AD) purportedly due to the triplication of the amyloid precursor protein (APP) gene, located on chromosome 21, which causes an over-expression of amyloid-beta (Aβ)." (PMID 33879062, 2021). "The assertion describes a gene-disease association (dgn-gda) between the NCBI gene amyloid beta precursor protein (miriam-gene:351) and the Alzheimer’s disease (lld:C0002395)." (PMID 33816986, 2021). "For instance, DS is the leading genetic risk factor for early-onset Alzheimer’s disease (AD) due to the increased dosage of APP, a Hsa21 gene." (PMID 35126461, 2021). "Alzheimer’s disease has been investigated in rodent models using a long list of transgenic mouse lines that overexpress mutant forms of the human APP gene (often the Swedish mutation)." (PMID 34630027, 2021). "We then sought to establish that the association between zinc supplementation and improved Alzheimer's disease outcome was causal by using the APP/PS1 mouse model of Alzheimer's disease." (PMID 33597269, 2021). "APP was identified as the most linked hub gene in the CD-specific subnet, and it has an important role in the pathogenesis of Alzheimer’s disease (AD)." (PMID 34484291, 2021).
Alzheimer disease (continued). "As examples, duplications and triplications of SNCA have been shown to cause forms of Parkinson’s disease, while duplications of APP cause early onset Alzheimer’s disease (AD)." (PMID 34321086, 2021). "Eleven of those follow an autosomal-dominant inheritance pattern and span a wide range of phenotypes, including three genes linked to various dental issues (AMTN, ENAM, DSPP) and APP known to cause Alzheimer disease when duplicated." (PMID 33315133, 2021). "As in other CNS areas, retinal neurons express amyloid beta precursor protein (APP), whose expression in Alzheimer’s disease patients has been linked to retinal ganglion cell (RGC) death." (PMID 34768774, 2021). "Brain-specific Alzheimer’s disease-associated aneuploidy/CIN more commonly involves chromosome 21 (note: APP (Amyloid Beta Precursor Protein) gene is located on chromosome 21)." (PMID 34069648, 2021). "Commonly used transgenic mouse models with human APP transgenes carrying familial mutations that produce high Aβ levels in the central nervous system recapitulate important features of Alzheimer disease." (PMID 34525093, 2021). "The presence of three copies of APP because of duplication mutations predispose familial Alzheimer's disease with complete penetrance." (PMID 33539581, 2021). "Alzheimer’s disease is also associated with mutations in nuclear DNA genes, such as APP, PSEN1, PSEN2, and APOE." (PMID 33445687, 2021). "In a small percentage of patients, Alzheimer’s disease (AD) is characterized by an early onset due to a mutation in one of three identified genes: amyloid-beta precursor protein (AβPP), Presenilin 1 (PSEN1), and Presenilin 2 (PSEN2)." (PMID 32581318, 2021). "Deficiency of NLRP3 and caspase-1 resulted in protection from cognitive impairment and memory loss in an APP/PS1 mouse model of Alzheimer's disease." (PMID 33534121, 2021). "Mutation A713T in the amyloid precursor protein (APP) has been linked to cases of Alzheimer’s disease (AD), cerebral amyloid angiopathy (CAA) and cerebrovascular disease." (PMID 35052700, 2021). "This increases AChE activity in the cortex and levels of oxidative stress and proinflammatory cytokines in the hippocampus, as well as increased levels of APP and Tau by producing amyloid beta to induce neurodegeneration that can cause Alzheimer's disease." (PMID 33987539, 2021). "The entity labels amyloid beta precursor protein and Alzheimer’s disease are taken respectively from the NCBI and Linked Life Data platforms." (PMID 33816986, 2021). "Mutations of PLD3 are considered to be a genetic factor involved in late onset Alzheimer’s disease associated with an increased processing of APP to Aβ." (PMID 34440765, 2021). "BACE catalyzes the rate-limiting first step in the sequential proteolytic cleavage of amyloid precursor protein (APP) to generate Aβ, which is deposited in the amyloid plaques associated with Alzheimer’s disease (AD)." (PMID 34679674, 2021). "BACE2 is a molecule that has been well studied in neurodegenerative diseases as the enzyme cleaving APP, the precursor of amyloid-β peptides (Aβ), a hallmark of Alzheimer’s disease." (PMID 33413577, 2021). "The mice used in this study expressed a human isoform of APP with the Swedish mutation, which causes high levels of Aβ and early onset of Alzheimer disease." (PMID 34204545, 2021). "Although the detailed mechanisms remain to be elucidated, the trafficking and proteolytic processing of the amyloid precursor protein (APP) have been implicated in Alzheimer’s disease (AD)." (PMID 33669482, 2021). "Alzheimer’s disease (AD) is implicated in the imbalance of several proteins, including Amyloid-β (Aβ), amyloid precursor protein (APP), and BACE1." (PMID 34577601, 2021). "Previous studies have shown that Rab5 activation mediates neuronal apoptosis caused by a familial Alzheimer’s disease (AD) mutant of amyloid precursor protein (APP) and that LAMP1 plays a role in KA-mediated apoptotic neuronal death." (PMID 33445746, 2021).
Alzheimer disease (continued). "This approach highlighted the involvement of FERMT2 (or Kindlin-2), a genetic risk factor of Alzheimer’s disease (AD), as a potential key modulator of axon guidance, a neuronal process that depends on the regulation of APP metabolism." (PMID 33144711, 2021). "Sequential cleavage of the amyloid precursor protein (APP) by two proteases generates the amyloid-β (Aβ) peptides associated with Alzheimer’s disease (AD)." (PMID 33513738, 2021). "In Alzheimer’s disease (AD), the degeneration of cortical and limbic structures is associated with mutation of APP (Amyloid-beta precursor protein) and presenilin-1, and with defect of ETC complex IV." (PMID 34679652, 2021). "People with Down syndrome (DS) are particularly susceptible to Alzheimer's disease (AD) due to the triplication of the amyloid precursor protein (APP) gene." (PMID 33748396, 2021). "γ-Secretase is responsible for the proteolysis of amyloid precursor protein (APP) into amyloid-beta (Aβ) peptides, which are centrally implicated in the pathogenesis of Alzheimer’s disease (AD)." (PMID 33571524, 2021). "Among replicated genes is the amyloid precursor protein (APP) gene – a primary genetic substrate of early-onset Alzheimer’s disease (AD) and BFCN loss in DS patients." (PMID 33763235, 2021). "Deposition in the brain of the 39- to 43-amino acid APP is a hallmark of Alzheimer disease (AD), a frequent complication of DS patients after the age of 30 years." (PMID 34136475, 2021). "Astrocyte accumulation is one of the earliest neuropathological changes in Alzheimer’s disease (AD), and amyloid precursor protein (APP) is the hallmark of AD." (PMID 33800526, 2021). "Individuals with Down syndrome (DS) constitute a population at ultrahigh risk of developing Alzheimer disease (AD) because of trisomy of chromosome 21, which harbors the APP (amyloid precursor protein; OMIM 104760) gene." (PMID 34228042, 2021). "Apart from that, a familial form of Alzheimer’s disease is also known, which is related to mutations in amyloid precursor protein (APP), PS1 presenilin 1 (PS1), and presenilin 2 (PS2) genes." (PMID 33374338, 2020). "Mutations in the gene for the amyloid precursor protein (APP) have been linked to the inherited Alzheimer’s disease." (PMID 32231018, 2020). "Macropinocytosis is also potentially implicated in the aetiology of Alzheimer’s disease through the regulation of amyloid precursor protein (APP) processing." (PMID 32756454, 2020). "Although APP is mostly associated with Alzheimer’s disease, many recent studies have described its impact on cancer." (PMID 32228434, 2020). "Down syndrome (DS) has been conceptualized by the International Working Group for Alzheimer’s disease (AD) as a genetically determined form of AD due to the triplication of the gene encoding amyloid precursor protein (APP), among others." (PMID 32807227, 2020). "The M722K mutation of APP has been further confirmed in the Chinese Familial Alzheimer’s Disease Network (CFAN) cohort study." (PMID 32235595, 2020). "PDAPP mice are genetically modified to reproduce a mutation found in the amyloid precursor protein (APP) gene in dominantly inherited forms of Alzheimer's disease." (PMID 32256202, 2020). "They identified thousands of variant genomic cDNAs (gencDNA) of the amyloid precursor protein (APP) gene in neurons of Alzheimer’s disease brains." (PMID 32411177, 2020). "The alteration of amyloid precursor protein (APP) proteolysis is a hallmark of Alzheimer's disease (AD)." (PMID 33282112, 2020). "Here, the efficacy of TGN in restoring amyloid β (Aβ)-induced axonal degeneration and in improving memory function was investigated in Alzheimer’s disease 5XFAD model mice that overexpress mutated APP and PS1 genes." (PMID 33009465, 2020). "Familial cases of Alzheimer’s disease (AD) are rare and are caused due to the mutations in the amyloid precursor protein (APP) or presenilins (PS1 and PS2)." (PMID 32626703, 2020).